ADA (adenosine deaminase)
Diseases named in the same sentence as ADA in open-access papers (continued):
Sharing a sentence is not in itself a finding about the gene and the disease.
Pleural effusion (continued). "In addition, TBP was independently associated with lymphocytes ≥ 35% and a lactate dehydrogenase (LD)/ADA ratio < 18 in pleural effusion." (PMID 38178065, 2024). "The diagnosis in this non-definite case relied on clinical and laboratory findings, including a lymphocyte-predominant exudative pleural effusion with high levels of adenosine deaminase and a clinical response to treatment leading to full resolution of symptoms and findings." (PMID 38393118, 2024). "However, even if the ADA level of pleural effusion exceeds 40 IU/L, there is a possibility for a disease other than TBP including parapneumonic effusion (PPE) and malignant pleural effusion (MPE)." (PMID 38178065, 2024). "In patients with very high levels of pleural effusion ADA, hMPE should be considered." (PMID 38178065, 2024). "Mean ± SD and p-value for ADA/CRP ratio for pleural effusions." (PMID 39205740, 2024). "Moreover, the expression of sCD46, sCD55, and sCD59 in pleural effusion was negatively correlated with ADA." (PMID 36820087, 2023). "TB pleurisy was confirmed bacteriologically in 22.1% of cases, and the remaining cases were clinically diagnosed in the case of exudative pleural effusion with elevated adenosine deaminase and exclusion of parapneumonic effusion and malignancy by chest computed tomography (CT) scan and cytology." (PMID 37719730, 2023). "In addition, further research is needed to explore how ADA, the levels of which are increased in various pleural effusions, acts differently and how we distinguish between these results." (PMID 35268372, 2022). "In addition to these modalities, there are at least two biomarkers showing promising results in the early diagnosis of pleural effusions: adenosine deaminase (ADA) and acute-phase proteins like C-reactive protein (CRP)." (PMID 34179342, 2021). "We describe a patient with IgG4-related pleural effusion who exhibited a high concentration of ADA." (PMID 33726002, 2021). "In addition, studies have reported that the combination of monocyte/leukocyte (MONO/LEU) ratio and pleural effusion Adenosine deaminase (ADA) test had up to 98% specificity in TBP diagnosis." (PMID 33816527, 2021). "Although exudative pleural effusion with high ADA and lymphocyte predominance is a characteristic of tuberculous pleuritis, other diseases might be present." (PMID 33926544, 2021). "The primary aim of the study was to assess the predictive accuracy of procalcitonin (PCT) and pentraxin-3 (PTX-3) in comparison to other biochemical markers such as C-reactive protein (CRP), and adenosine deaminase (ADA) in the differential diagnosis of pleural effusions." (PMID 34179342, 2021). "This study found that the combined detection of pleural effusion IL-33, ADA and peripheral blood T-SPOT.TB could further improve the sensitivity and specificity of TPE diagnosis." (PMID 34425761, 2021). "These tests have recognized limitations in clinical practice, such as low sensitivity, lengthy delay, or invasiveness; as a result, multiple biomarkers in pleural effusion have been investigated, including adenosine deaminase (ADA) and interferon-gamma (IFN-γ)." (PMID 32571326, 2020). "Another study from India reported that all patients with TB pleural effusion had elevated ADA levels and there was a statistical significant association (p < 0.05) of ADA levels in differentiating TB pleural effusion from non-TB pleural effusion." (PMID 31016096, 2019). "In their study the ADA levels were significantly higher in TB pleural effusion patients." (PMID 31016096, 2019). "In this context, among routinely performed pleural fluid analyses, neutrophilic predominance is indicative of a parapneumonic pleural effusion, and a raised ADA level is highly suggestive (specificity of 92%) for TB, but to date, no test is specific to “rule-in” MPE." (PMID 28070157, 2016).
Pleural effusion (continued). "In conclusion, the occurrence of bilateral pleural effusion with an elevated ADA activity as the initial symptom in MM is extremely rare, and may result in a delayed diagnosis." (PMID 25667674, 2015). "Her adenosine deaminase (ADA) level in her right pleural effusion was 50.4IU/L." (PMID 26271927, 2015). "For the early diagnosis of TP, biomarkers in pleural effusion such as adenosine deaminase and interferon-gamma have been shown to be helpful, but further investigations are needed for the application of nucleic acid amplification tests and interferon-gamma release assays." (PMID 21338482, 2011). "Tuberculous pleural effusions are not always easy to diagnose but the presence of a lymphocyte-rich exudate associated with an increased adenosine deaminase level and a positive skin test result are highly sensitive diagnostic signs." (PMID 19175931, 2009). "ADA level more than 100 IU/L observed only in cases of tubercular pleural effusion so from the study we concluded that if ADA level of more than 100 IU/L is taken as cut off point it is exclusively seen in cases of tubercular pleural effusion." (PMID 20165661, 2008). "However, high ADA levels can also be observed in lymphoma and myeloma‐related pleural effusions." (PMID 39563685, 2024). "However, he had strong evidence of an exudative pleural effusion as per Lights criteria (an empyema with a pH of 7.2) and a high likelihood of tuberculosis with significantly high ADA levels and positive GeneXpert® test (a cartridge-based nucleic acid amplification test)." (PMID 39697914, 2024). "Finally, we attempted to categorize pleural effusions based on both ADA and CRP levels." (PMID 34575641, 2021). "Therefore, we hypothesized that, combined with ADA test, pleural effusion mononuclear cells count may contribute to the diagnosis of TBP." (PMID 31921874, 2019). "However, the ADA level in the right pleural effusion was elevated in our case." (PMID 26271927, 2015). "Diagnosis of TPE based on ADA levels in pleural effusion may have a limitation." (PMID 22889060, 2012). "There should be a high degree of suspicion regarding the possibility of lymphoma in case of increased mononuclear cells with elevated ADA and LDH in exudative pleural effusion." (PMID 41480553, 2025). "In pleural effusion, NLR (AUC: 0.83, p = 0.02), ADA (AUC: 0.8, p = 0.02), and C-reactive protein in blood (AUC: 0.87, p = 0.003) demonstrated robust diagnostic capabilities." (PMID 38742106, 2024). "Overall, adenosine deaminase (ADA) levels were increased in 9 cases with lymphocytic exudate (22%), and LDH levels were increased in 26 pleural effusions (26; 28%)." (PMID 37241003, 2023). "Biochemical examination of pleural effusion: Glucose: 7.38 mmol/L; Protein: 43.4 g/L; Albumin: 28.0 g/L; Chlorine: 108.9 mmol/L; Pleural LDH: 636 U/L; ADA:2U/L." (PMID 36747130, 2023). "Combined detection of Pleural effusion of Serum ADA, IGRA, Effusion ADA, Effusion ADA/Serum ADA and Effusion LDH/Effusion ADA can improve the diagnostic efficacy of tuberculous pleurisy." (PMID 37940883, 2023). "IGRA, CRP, ESR, serum TP, ALB, ADA, LDH, Pleural effusion TP, ALB, ADA, and LDH are the primary examinations for hospitalized patients." (PMID 37940883, 2023). "Pleural fluid cell count and differentials, glucose level, adenosine deaminase (ADA), fluid GeneXpert for Mycobacterium tuberculosis (MTb), fluid culture, and cytology are currently used for further evaluation of exudative pleural effusions." (PMID 35874904, 2022). "The pleural effusion of patients with IgG4-related pleural effusion showed higher TP levels (P < .001) and lower LDH (P < .001) and ADA levels (P = .002) than those with tuberculous pleurisy." (PMID 33726002, 2021). "Pleural fluid levels of ADA, INF-γ, and IL-27 are present in significantly higher concentrations in patients with TPE than those in patients with other types of pleural effusion." (PMID 31455239, 2019).
Pleural effusion (continued). "Through the comparison between the level of ADA and CEA in pleural effusion in TPE and MPE categories, pleural ADA median level was significantly higher (P < 0.001) in TPE compared to MPE." (PMID 30651075, 2019). "Among the widely-used biomarkers, the adenosine deaminase (ADA) and carcinoembryonic antigen (CEA) in pleural effusion were better biomarkers with high sensitivity and specificity to discriminate TPE and MPE." (PMID 30651075, 2019). "Biochemical tests routinely and universally performed in clinical practice for investigating pleural effusion are serum lactate dehydrogenase (LDH) and protein, pleural LDH, protein, differential cell count, pH, glucose, and adenosine deaminase (ADA)." (PMID 28070157, 2016). "The cell infiltrate profile, microbiological examination, adenosine deaminase (ADA) level, and other biochemical tests of pleural effusion lack sensitivity and specificity." (PMID 26503802, 2015). "The pleural effusion parameters were as follows: protein: 40.6 g/L, lactic dehydrogenase (LDH): 121 IU/L, WBC count: 920/μl with 70 % lymphocytes, RBC count: 2500/μl, adenosine deaminase (ADA): 121 IU/L, and glucose: 7.83 mmol/L (measured on June 4 (day 2))." (PMID 26395579, 2015). "Estimation of adenosine deaminase (ADA) and IFN-γ in pleural fluid has been used widely as biochemical markers in the diagnosis of TB pleural effusion." (PMID 20419090, 2010). "Performance outcomes of ADA, microbiological investigations, a nucleic-acid-amplification-test [NAAT] and unstimulated IFN-γ levels for the diagnosis of TB pleural effusion in 74 TB suspects when the definite and probable TB groups are combined." (PMID 19277111, 2009). "Our case series reinforces the point that neither a normal ADA nor a negative PCR excludes TB in patients with exudative pleural effusions and systemic symptoms." (PMID 40585722, 2025). "Several biomarkers have recently been applied to the diagnosis and differentiation of TPE in China and abroad, including adenosine deaminase (ADA), lactate dehydrogenase (LDH), C-reactive protein (CRP), and several inflammatory cytokines in serum and pleural effusion." (PMID 38750432, 2024). "Pleural fluid analysis suggested low adenosine deaminase (ADA) and exudative pleural effusion." (PMID 39290927, 2024). "ADA levels exceeding 40 IU/L are not exclusive to lymphoma, as similar elevations can also be observed in pleural effusion secondary to leukemia or multiple myeloma." (PMID 38178065, 2024). "The level of IL-32 was positively correlated with ADA, LDH, and nucleated cell counts, generally related to total protein in pleural effusions (all P < 0.001), and negatively correlated with glucose (P < 0.05) but was not correlated with the mononuclear cell ratio (P > 0.05)." (PMID 35880892, 2022). "Pleural fluid cell count and differentials, glucose level, adenosine deaminase (ADA), fluid GeneXpert for Mycobacterium tuberculosis (MTb), fluid culture, and cytology are currently employed in the further evaluation of exudative pleural effusions." (PMID 35874904, 2022). "There was no TPE case in the group presenting ADA level < 40 IU/L, as in patients with lymphocyte dominant pleural effusion." (PMID 35534515, 2022). "In conclusion, current data suggest that the determination of ADA, CD4+IL-9+, and Treg cells in pleural effusion may be an important diagnosis marker for TPE." (PMID 34925358, 2021). "The aim of this study was to determine whether the pleural levels of two biological markers, ADA- CRP, and their combined function, could help us discriminate malignant (MPE), parapneumonic (PPE) and tuberculous (TPE) pleural effusions." (PMID 34575641, 2021). "ADA levels were found to be significantly higher in tuberculous exudative vs. nontuberculous exudative pleural effusions." (PMID 34179342, 2021). "In our study, among the 3 ADA positive cases in no pleural TB group, 1 subject is suffered from parapneumonic pleural effusion and two other cases are suffered from lymphoma." (PMID 24386296, 2013).
Pleural effusion (continued). "In cases with non-tubercular exudative pleural effusion the ADA levels were found to be consistently below the cut-off." (PMID 21811524, 2010). "In conclusion, in this study, ADA levels in non-tuberculous exudative pleural effusions rarely exceeded the cut-off; set for tuberculous disease." (PMID 21811524, 2010). "In this study, ADA levels in nontuberculous exudative pleural effusions rarely exceeded the cut-off; set for tuberculous disease." (PMID 21811524, 2010). "The purpose of this study is to find out the role of ADA levels in differentiation of tuberculous and non-tuberculous exudative pleural effusions of different etiologies." (PMID 21811524, 2010). "Present study confirms that t ADA level in tubercular pleural effusion is increased and in non tubercular pleural effusion ADA level did not exceed to100 IU/L." (PMID 20165661, 2008). "Therefore, utilizing parameters such as ADA, LDH, CRP, and ESR together could enhance the accuracy of distinguishing between TPE and pleural effusions of other origins." (PMID 38750432, 2024). "Differential diagnosis of pleural effusion is usually determined through cytology and bacterial culture of the pleural effusion, cell differentiation, and measurement of lactate dehydrogenase (LDH) levels, total protein, adenosine deaminase (ADA), and hyaluronic acid in the pleural effusion." (PMID 39435223, 2024). "Therefore, pleural effusion with high ADA levels should not be diagnosed simply as tuberculous pleurisy." (PMID 36131272, 2022). "Because of the high concentrations of ADA in the pleural effusion, we could not distinguish between IgG4-related pleural effusion and tuberculous pleurisy." (PMID 33726002, 2021). "Pleural levels of a number of biomarkers have been proposed as aids in the diagnosis of TPE, including adenosine deaminase (ADA) and interferon-γ(INF-γ), both of which are present in patients with TPE at significantly higher concentrations than in patients with other types of pleural effusion." (PMID 29216864, 2017). "In addition, the level of ADA, which is related to the proliferation of T lymphocytes, in the pleural effusion of our patient was not higher than that in patients with typical tuberculous pleurisy." (PMID 24593234, 2014). "Adenosine deaminase level of less than 40 U/L practically excludes the tubercular etiology in exudative pleural effusion cases and thus may be useful in differentiating tuberculous etiology from others in exudative pleural effusion." (PMID 21811524, 2010). "However, due to non-standardized and costly ADA2 assays, total ADA levels in pleural effusion remain the primary marker in the clinical setting.The currently accepted ADA cut-off value is 40 U/L, but the threshold value ranges from 17.5 to 77 U/L among different studies and decrease with age." (PMID 38750432, 2024). "Besides being offered, HIV status was only known in 59 subjects, with only 3 cases of positivity (one undefined pleural effusion with positive ADA and negative IFN-γ and IP-10, one renal failure with all three biomarkers negative, 1 probable TB with all the biomarkers positive)." (PMID 30148839, 2018). "Another limitation was that the patients with TPE and PPE included in our study were not representative of those with pleural effusions caused by other conditions such as connective tissue diseases or MPE, who may also have a high pleural fluid ADA or LDH levels." (PMID 29202740, 2017). "The levels of carcinoembryonic antigen, adenosine deaminase, and LDH in the pleural effusions were nonspecific for these 19 patients." (PMID 39618817, 2024). "We quantified the expression of HGF, adenosine deaminase (ADA), and interferon gamma (IFN-γ) in pleural effusion (PE) in 97 TPE subjects and 116 non-TPE subjects using an enzyme-linked immunosorbent assay (ELISA) or a fully automatic biochemical analyzer." (PMID 37485530, 2023).
Pleural effusion (continued). "Adenosine deaminase (ADA) activity, lymphocyte count, lactate dehydrogenase (LDH), and C-reactive protein (CRP) of pleural effusion in pleural TB group were higher than in the no pleural TB group (all p-values < 0.05)." (PMID 35250926, 2022). "We performed correlation analysis and found that frequency of IFN-γ-producing MAIT cells was not correlated with age and sex of the patients, levels of ADA, LDH, total proteins, glucose concentration and ratio of mononuclear cells in pleural effusions." (PMID 27586092, 2016). "Performance outcomes of ADA, microbiological investigations, a nucleic-acid-amplification-test [NAAT] and unstimulated IFN-γ levels for the diagnosis of TB pleural effusion in 74 TB suspects using the definite and non-TB groups." (PMID 19277111, 2009). "However, immune function tests, including lymphocytes and their subsets in both peripheral blood and pleural effusion, were not conducted to assess peripheral and local lymphocyte function in the pleural cavity for a more comprehensive analysis of the influencing factors of IGRA and ADA." (PMID 39445216, 2024).